MAPK10 (mitogen-activated protein kinase 10)
Description:
Serine/threonine-protein kinase involved in various processes such as neuronal proliferation, differentiation, migration and programmed cell death. Extracellular stimuli such as pro-inflammatory cytokines or physical stress stimulate the stress-activated protein kinase/c-Jun N-terminal kinase (SAP/JNK) signaling pathway. In this cascade, two dual specificity kinases MAP2K4/MKK4 and MAP2K7/MKK7 phosphorylate and activate MAPK10/JNK3. In turn, MAPK10/JNK3 phosphorylates a number of transcription factors, primarily components of AP-1 such as JUN and ATF2 and thus regulates AP-1 transcriptional activity. Plays regulatory roles in the signaling pathways during neuronal apoptosis. Phosphorylates the neuronal microtubule regulator STMN2. Acts in the regulation of the amyloid-beta precursor protein/APP signaling during neuronal differentiation by phosphorylating APP. Also participates in neurite growth in spiral ganglion neurons. Phosphorylates the CLOCK-BMAL1 heterodimer and plays a role in the photic regulation of the circadian clock. Phosphorylates JUND and this phosphorylation is inhibited in the presence of MEN1.
Synonyms: SAPK1b; JNK3; JNK3A; PRKM10; p493F12; p54bSAPK
Tractability: Small molecule: a drug acting on it is in phase 2 or 3 trials; a structure with a bound ligand is known; a high-quality ligand is known; it has a high-quality binding pocket; it belongs to a druggable protein family. Antibody: its Gene Ontology location is reachable by antibodies, with medium confidence. PROTAC: it is named in the literature on targeted protein degradation; ubiquitination databases record sites on it; its protein half-life has been measured; a small molecule that binds it is known. Other modalities: a drug acting on it is in phase 2 or 3 trials.
Target class: Protein Kinase; CMGC protein kinase JNK subfamily; Enzyme; Kinase; CMGC protein kinase group; CMGC protein kinase MAPK family
Chemical probes: JNK-IN-7 (high quality), JNK3-IN-8, PD134333
Gene: Protein-coding gene on chromosome 4 (85,990,007 to 86,594,625, reverse strand). Ensembl gene ENSG00000109339.
Subcellular location: Cytoplasm; Membrane; Nucleus; Mitochondrion
Subcellular location (Human Protein Atlas): Nucleoplasm
Pathways (Reactome):
Immune System: Activation of the AP-1 family of transcription factors; FCERI mediated MAPK activation; JNK (c-Jun kinases) phosphorylation and activation mediated by activated human TAK1
Cellular responses to stimuli: Oxidative Stress Induced Senescence
Gene Ontology:
Molecular function: protein binding; JUN kinase activity; MAP kinase kinase activity; ATP binding; MAP kinase activity; protein kinase activity; protein serine kinase activity
Biological process: protein phosphorylation; cellular senescence; Fc-epsilon receptor signaling pathway; JNK cascade; regulation of circadian rhythm; response to light stimulus; signal transduction; MAPK cascade
Cellular component: nucleoplasm; cytoplasm; cytosol; mitochondrion; plasma membrane; membrane; nucleus
Genetic constraint (gnomAD): Loss-of-function variants: 15 observed, 42.81 expected, observed/expected ratio (o/e) 0.35, 90% interval 0.23 to 0.54. The upper end of that interval is the gene's LOEUF score, 0.54, which puts it in group 2 of 6, group 1 being the genes least tolerant of losing a copy. Missense variants: 271 observed, 492.34 expected, observed/expected ratio (o/e) 0.55, 90% interval 0.5 to 0.61. Synonymous variants: 163 observed, 179.55 expected, observed/expected ratio (o/e) 0.91, 90% interval 0.8 to 1.03.
Homologues: Orthologues: chimpanzee MAPK10 (100% identical), macaque MAPK10 (100% identical), mouse Mapk10 (99% identical), pig MAPK10 (99% identical), rat Mapk10 (99% identical), rabbit MAPK10 (99% identical), zebrafish mapk10 (96% identical), dog MAPK10 (90% identical), tropical clawed frog mapk10 (88% identical), guinea pig MAPK10 (87% identical), Caenorhabditis elegans kgb-1 (40% identical), Caenorhabditis elegans kgb-2 (36% identical), and 9 more. Paralogues in human: MAPK8 (84% identical), MAPK9 (77% identical), MAPK14 (39% identical), MAPK11 (38% identical), MAPK12 (37% identical), MAPK13 (36% identical), MAPK7 (33% identical), MAPK1 (32% identical), MAPK3 (31% identical), NLK (30% identical), MAPK15 (29% identical), MAPK6 (26% identical), and 7 more.
Diseases named in the same sentence as MAPK10 in open-access papers:
MAPK10 is named in the same sentence as 119 diseases in open-access papers, as found by Europe PMC text mining. Sharing a sentence is not in itself a finding about the gene and the disease. The quoted sentences say what the papers report.
Alzheimer disease (15 papers, 2020 to 2025). A progressive, neurodegenerative disease characterized by loss of function and death of nerve cells in several areas of the brain leading to loss of cognitive function such as memory and language. "Remarkably, some of them are targeted by more than one miRNA, such as APBA2, which are involved in the “Alzheimer disease–amyloid secretase pathway” together with the CHRNA7 and MAPK10 genes, corroborating the importance of the regulation of their gene expression in AD." (PMID 40243843, 2025). "During the analysis, DTGs included in the Alzheimer disease-amyloid secretase pathway were Prkcd (protein kinase C δ [PKC-δ]) and Mapk10 (mitogen-activated protein kinase 10 [Mapk10])." (PMID 35056627, 2022). "Interestingly, again, MAPK10 and CHRNA7—Alzheimer’s disease pathway-related genes—were recognized as the putative targets of specific brain-expressed lncRNAs." (PMID 40243843, 2025). "Additionally, AST4 expressed a high level of MAP3K5, MAPK10, and TUBB3, which are enriched in Alzheimer's disease–related pathways (hsa05010, P = 2.0 × 10−07)." (PMID 38091510, 2022).
ischemia (12 papers, 2010 to 2021). A hypoperfusion of the BLOOD through an organ or tissue caused by a PATHOLOGIC CONSTRICTION or obstruction of its BLOOD VESSELS, or an absence of BLOOD CIRCULATION. "Collateral artery diameters and circumference of whole-body Mapk10 knockout as well as neural Mapk10-deficient mice were significantly higher than control littermates after hindlimb ischemia." (PMID 31530804, 2019). "Taken together, these results demonstrate that neural Mapk10 deletion promotes pathways involved in improved blood flow recovery after ischemia." (PMID 31530804, 2019). "More importantly, disruption of Mapk10 (JNK3) is neuroprotective in a mouse model of ischemia through a complex and poorly understood mechanism." (PMID 28961383, 2017). "There was a marked increase in Mapk10 RNA expression in peripheral nerves with ischemia without any change in other members of the JNK family (Mapk8 and Mapk9) that are expressed in neurons." (PMID 31530804, 2019).
Obesity (11 papers, 2013 to 2025). Accumulation of substantial excess body fat. "Likewise, deactivation of MAPK10 in neurons induces weight gain and alters insulin and leptin signaling, characteristics associated with obesity." (PMID 40140215, 2025). "We used a pair-feeding protocol to test whether the increased obesity of Mapk10-/- mice compared with WT mice was caused by greater food consumption." (PMID 26910012, 2016). "In addition, previous report has shown that MAPK10 could block the hypothalamic-pituitary-thyroid axis, thereby reducing energy expenditure and promoting obesity." (PMID 33445426, 2021). "From this analysis, methylation data (β values) of cancer-related genes previously identified in the DNA of leukocytes from patients with obesity after following a VLCKD to lose weight were isolated (CCND1, MAPK10, GLI2, LAMC3 and CTNNA2)." (PMID 40140215, 2025). "JNK activity has been associated with obesity in a mouse model, where the absence of JNK1 (MAPK8), a protein in the same family as MAPK10, protects against the obesity-induced insulin resistance." (PMID 24278029, 2013).
breast carcinoma (9 papers, 2020 to 2023). "Previous reports indicated that down-regulation of the MAPK10 gene in the tumor microenvironment promotes the migration and metastasis of breast cancer, nasopharyngeal carcinoma, and cervical cancer." (PMID 34408980, 2021). "The expression levels of Prss14/epithin (ST14), PKCβ (PRKCB), and three JNKs (MAPK8, MAPK9, and MAPK10) in more aggressive ER-negative (ER−) and less aggressive ER-positive (ER+) breast cancer patients were compared individually in the plot." (PMID 32241917, 2020). "Likewise, miR-21-5p inhibits mitogen-activated protein kinase 10 to promote the progression of breast cancer." (PMID 34889164, 2021). "PSME2, MAPK10, EIF4EBP1 were screened as the prognostic genes in breast cancer." (PMID 37035151, 2023). "Interestingly, there were multiple well-known TSGs, including MAPK10, a well-studied TSG in esophageal cancer, cervical cancer, and breast cancer." (PMID 34001209, 2021).
hepatocellular carcinoma (9 papers, 2013 to 2025). A malignant tumor that arises from hepatocytes. "Genetic and epigenetic alterations in human MAPK10 have been implicated in cancers such as lymphomas and lung and liver carcinomas." (PMID 23813869, 2013). "MAPK10 is also associated with the prognosis of renal cell carcinoma and hepatocellular carcinoma." (PMID 37285835, 2023). "In hepatocellular carcinoma, MAPK10 serves as a prognostic marker of the immunosuppressive tumor microenvironment, where its downregulation correlates with diminished overall survival." (PMID 41472741, 2025). "Dysregulated miR-27a-3p enhances the proliferation and migration capability of nasopharyngeal carcinoma cell by regulating the expression level of MAPK10, and Circ_0000515 can also drive hepatocellular carcinoma progression by targeting MAPK10." (PMID 37768204, 2023). "Here, we investigated the expression status of MAPK10 in HCC and used transcriptomics to characterize the impact of MAPK10 expression on the gene expression landscape of the tumor microenvironment in human hepatocellular carcinoma." (PMID 34408980, 2021). "It has been reported that MAPK10 can regulate the inflammatory response in human osteoarthritis and astrocytes, and MAPK11 can regulate the inflammatory response in human hepatoma cells and mice." (PMID 37570275, 2023). "The specific mechanism of MAPK10 acting on melanoma has not been proven, and the carcinogenic effect of MAPK10 in hepatocellular carcinoma, renal cell carcinoma and gastric cancer has been extensively studied." (PMID 37666853, 2023).
Cognitive impairment (7 papers, 2015 to 2025). Abnormal cognition is characterized by deficits in thinking, reasoning, or remembering. "A MAPK10/JNK3 truncation mutation has previously only been associated with cognitive disorders." (PMID 26339226, 2015). "Interestingly, the recent characterizations of MAPK10/JNK3 truncation mutations, in two unrelated patients, proved that the partial loss of JNK3 function induces an altered regulation of a set of post-synaptic proteins correlated with cognitive disorders." (PMID 32998477, 2020).
diabetes (7 papers, 2016 to 2026). "MAPK10 might become a potential target for future cardioprotective therapeutic strategies for diabetes-associated CVDs." (PMID 35941186, 2022). "MAPK10 was identified as a critical gene in diabetes mellitus-induced atrial fibrillation in mice." (PMID 37680885, 2023).
esophageal cancer (6 papers, 2020 to 2025). A primary or metastatic malignant neoplasm involving the esophagus. "For instance, ZNF471 activates MAPK10/JNK3 signaling pathway but is frequently silenced by promoter CpG methylation in esophageal cancer." (PMID 40612670, 2025). "Previous studies found a deletion at 4q21.3 in two esophageal carcinoma cell lines and found that Mapk10 was located in this deleted region with a 633bp bidirectional promoter, which was a typical CpG island, as well as that Mapk10 was expressed in all normal adult tissues." (PMID 33604188, 2021). "ZNF471 was found to activate the expression of MAPK10/JNK3 and PCDH family genes, and further enhance MAPK10 signaling and downstream gene expression in esophageal cancer." (PMID 38169650, 2024). "In esophageal cancer, ZNF471 functions as a TSG through activating MAPK10/JNK3 signaling." (PMID 33203470, 2020).
gastric cancer (6 papers, 2021 to 2025). A primary or metastatic malignant neoplasm involving the stomach. "The underlying mechanism is that the downregulation of MAPK10 inhibits the proliferation, migration, and invasion of gastric cancer cells and induces apoptosis." (PMID 40429988, 2025). "Studies have also shown that miR-335-5p can exert its suppressive effect on gastric cancer by targeting MAPK10." (PMID 40429988, 2025). "The tumor suppressor miR-335-5p was able to inhibit gastric cancer by targeting MAPK10." (PMID 39689118, 2024).
lymphoma (6 papers, 2007 to 2025). A malignant (clonal) proliferation of B- lymphocytes or T- lymphocytes which involves the lymph nodes, bone marrow and/or extranodal sites. "Only mitogen-activated protein kinase 10 (MAPK10), the best classical lymphoma marker, reaches top ranks." (PMID 19455257, 2007). "Previously, it was identified that Mapk10 (JNK3) could be inactivated in multiple lymphomas and carcinomas by epigenetic methylation, albeit only few studies have addressed this concern." (PMID 33604188, 2021).
ovarian carcinoma (6 papers, 2020 to 2025). A malignant neoplasm originating from the surface ovarian epithelium. "Decreased expression levels of MAPK10 are associated with worse survival and worse prognosis in cancer, being found downregulated in breast or ovarian cancer, among others." (PMID 40140215, 2025). "Knocking down MAPK10 suppressed ovarian cancer cell growth and migration." (PMID 35459184, 2022). "The downregulation of MAPK10 contributes to the suppression of ovarian cancer." (PMID 33482821, 2021). "The programmed cell death mediated by MAPK10 and STAT4 in ovarian cancer deserves further study." (PMID 37095524, 2023).
Insulin resistance (5 papers, 2013 to 2026). Increased resistance towards insulin, that is, diminished effectiveness of insulin in reducing blood glucose levels. "Consequences of the increased HFD feeding behavior of Mapk10-/- mice include increased hyperinsulinemia and hyperleptinemia, increased blood lipid concentrations, decreased glucose tolerance, and increased insulin resistance when fed a HFD, but not a CD." (PMID 26910012, 2016).
nasopharyngeal carcinoma (5 papers, 2017 to 2024). A carcinoma arising from the nasopharyngeal epithelium. "Mapk10, a target of miR-27a-3p, is envolved in nasopharyngeal carcinoma cell proliferation and migration." (PMID 28725177, 2017).
type 2 diabetes mellitus (5 papers, 2015 to 2023). A type of diabetes mellitus that is characterized by insulin resistance or desensitization and increased blood glucose levels. "Not only PPARG but CSNK2A1, MAPK10, and MTOR are known as T2D genes and participate on parts of T2D associated pathways such as type II diabetes mellitus, insulin signaling pathway, and Wnt signaling pathway in KEGG." (PMID 26043787, 2015). "Moreover, the methylation level of genes related to type II diabetes mellitus was also prominently decreased, including Prkce, Prkcz, Adipoq, Tnf, Slc2a2, Prkcd, and Mapk10." (PMID 26881249, 2016). "The impact analysis also revealed the enrichment of the “Type II diabetes mellitus” pathway resulting from the upregulation of MAPK10 and IRS2 and the downregulation of CACNA1A and SOCS2, a signature that may upregulate the insulin receptor (INSR), PI3K, and insulin resistance." (PMID 36835058, 2023).
atherosclerosis (4 papers, 2018 to 2025). A disease characterized by the build-up of fatty material and calcium deposition in the arterial wall resulting in partial or complete occlusion of the arterial lumen. "It has also been reported that miR-155 negatively regulates inflammatory cytokine production and slows the progression of atherosclerosis because it controls the inflammatory response by repressing the mitogen-activated protein kinase 10 (MAP3K10) pathway." (PMID 40469388, 2025).
atrial fibrillation (4 papers, 2022 to 2024). A disorder characterized by an electrocardiographic finding of a supraventricular arrhythmia characterized by the replacement of consistent P waves by rapid oscillations or fibrillatory waves that vary in size, shape and timing and are accompanied by an irregular ventricular response. "Some studies have shown that MAPK10 plays a central role in atrial fibrillation in mice, and MAPK10 knockout can significantly reduce atrial inflammation." (PMID 36544491, 2022).
COVID-19 (4 papers, 2021 to 2023). A disease caused by infection with severe acute respiratory syndrome coronavirus 2. "A recent network pharmacology approach revealed the novel therapeutic targets of COVID-19 inflammation, including MAPK8 (JNK1), MAPK10 (JNK3), and BAD (Bcl-2-associated death promoter), which are involved in the RAS signaling pathway and autophagy." (PMID 36293117, 2022). "Our research suggests that BAD-Indomethacin's inhibition with the other two hub proteins, MAPK8-6MNA, MAPK10-Rofecoxib might play cumulative actions by inactivating the RAS signaling pathway against COVID-19." (PMID 33953223, 2021). "Other genes that have been annotated in public database KEGG for their role in the COVID-19 pathway include NLRP3 (NLR family pyrin domain containing 3), MAPK10 (mitogen-activated protein kinase 10), and PIK3CD (phosphatidylinositol-4,5-bisphosphate 3-kinase catalytic subunit delta)." (PMID 36800980, 2023). "The result suggested that the three NSAIDs' key mechanism against COVID-19 might be to inhibit inflammation of lung cells by inactivating the RAS signaling pathway, and blockers of MAPK8, MAPK10 and BAD might suppress cytokine storm." (PMID 33953223, 2021).
neuroblastoma (4 papers, 2016 to 2021). Neuroblastoma (NB) is the most common solid, extracranial childhood tumor. "We confirmed the association between neural Mapk10 expression and pro-angiogenic gene expression using the neuroblastoma cell line Neuro-2a (N2a)." (PMID 31530804, 2019).
cardiac hypertrophy (3 papers, 2022 to 2024). "Similarly, MAPK10 knockdown in db/db mouse hearts strongly reversed the deleterious effects, including hyperglycemia-induced cardiac hypertrophy, diastolic dysfunction and apoptosis." (PMID 35941186, 2022). "Similarly, tail vein injection of rAAV9-Sh-MAPK10 reversed the phenotype of the heart in db/db mice including cardiac hypertrophy and apoptosis in db/db mice." (PMID 35941186, 2022).
colon cancer (3 papers, 2017 to 2022). "Additionally, the most recent efforts directed toward the CDKN1A gene have demonstrated that downregulation of this gene leads to colon cancer progression, and similar results have been reported for MAPK10." (PMID 28178311, 2017). "For the top colon cancer MEGs, the consistent tumor suppressor genes included MAP2K4, MAPK10, RUNX3, WNK2 (the four genes were identified by the TSGene 2.0 database), BECN1, FASN, NAT1, and NR3C2." (PMID 33273919, 2020). "We observed that MAPK10 and CDKN1A were only altered in colon cancer (shown in cyan)." (PMID 28178311, 2017).
epilepsy (3 papers, 2019 to 2025). A brain disorder characterized by episodes of abnormally increased neuronal discharge resulting in transient episodes of sensory or motor neurological dysfunction, or psychic dysfunction. "Yet, the most prominent genes in the IESS condition, Grm8 (male) and Mapk10 (female), have documented implications in epilepsy." (PMID 40699779, 2025).
glioma (3 papers, 2017 to 2021). A benign or malignant brain and spinal cord tumor that arises from glial cells (astrocytes, oligodendrocytes, ependymal cells). "The results showed that MLK3 mRNA in human gliomas was negatively related to MAPK8, MAPK9, and MAPK10." (PMID 33692940, 2020).